CLDN18 (claudin 18)
Diseases named in the same sentence as CLDN18 in open-access papers (continued):
Sharing a sentence is not in itself a finding about the gene and the disease.
tumor (continued). "In the moderate-to-high CLDN18.2 expression subgroup (≥70% of tumor cells), 14% of patients achieved a partial response (PR) and 17% had stable disease (SD) with zolbetuximab treatment." (PMID 40136475, 2025). "To determine the durability of TAC T-cell responses in vivo, we evaluated the functional persistence of CLDN18.2-TAC T cells in a 54-day tumor rechallenge experiment." (PMID 39404622, 2025). "The third arm of the phase-II ILUSTRO trial covered three CLDN18.2 high or intermediate (CLDN18 staining is moderate to strong in 50%–75% of the tumor cells’ membranes) patient groups, who were treated with third-line or later zolbetuximab and pembrolizumab." (PMID 39941712, 2025). "For example, the FAST trial defined ≥ 40% of tumor cells with moderate-to-high (+2 to +3 on IHC) CLDN18.2 expression as the cutoff for positivity." (PMID 41374966, 2025). "The results of the bioinformatics analysis demonstrated significantly elevated CLDN18 mRNA levels in ICC versus adjacent non-tumor tissues (P < 0.05), with positive correlation between CLDN18 expression and advanced AJCC stage (P < 0.05)." (PMID 40951359, 2025). "Within a tumor, the superficial area tended to have a higher CLDN18-positive rate than the invasive front (P = 0.001)." (PMID 38724721, 2024). "We also display a highly hopeful prospect of applications in adoptive T-cell therapy, tumor vaccines, or other immunotherapies in clinic, which extend personalized treatment options for GC patients with CLDN18-ARHGAP gene fusion." (PMID 39164472, 2024). "Specifically, we genetically engineered two single chain variable fragments (scFv) onto cell membrane: anti-CD40 scFv for engaging with macrophages and anti-Claudin18.2 (CLDN18.2) scFv for interacting with tumor cells." (PMID 38468289, 2024). "Regarding PD, a recent study analyzed CLDN18 expression using effusion cell block samples, demonstrating a high concordance (83.7%) between primary tumor tissue and effusion cells." (PMID 38724721, 2024). "Across SPOTLIGHT and GLOW, the prevalence of CLDN18.2 positivity (≥ 75% of tumor cells demonstrating moderate-to-strong membranous CLDN18 staining) was 38.4%." (PMID 38954176, 2024). "OVA antigen presentation was subsequently checked by co-culturing BMMs with OVA-overexpressed CLDN18.2-postive tumor cells." (PMID 38468289, 2024). "Specifically in GC, CLDN18 appears to have different functions based on the level of expression in tumor cells." (PMID 38339430, 2024). "CLDN18 as a potential target for GC treatment, it has been identified to correlate with tumor size, aggressiveness, potential metastasis, and prognosis in GC patients." (PMID 38704377, 2024). "The frequencies of tumor-infiltrating NK cells and macrophages, as well as peripheral blood NK cells and monocytes, were comparable between CLDN18.2-positive and CLDN18.2-negative GCs." (PMID 39095563, 2024). "Looking at the subgroup with CLDN18.2 expression in ≥70% of tumor cells with efficacy data (n = 29), there was an ORR of 14% (n = 4) and 17% (n = 5) had stable disease." (PMID 38392051, 2024). "The aim of the present study was to obtain an overview of the overall status of the anecdotally reported CLDN18.2 prevalence in tubo-ovarian carcinoma across all histological subtypes and tumor sites." (PMID 38326579, 2024). "Our study reveals the potential value of CLDN18.2 for tumor prognosis and targeted therapy in various cancers, especially upper gastrointestinal tract cancers." (PMID 39555091, 2024). "Preclinical data of humanized anti-CLDN18.2 autologous CAR-T have demonstrated antigen-specific anti-tumor effects on GC." (PMID 38339430, 2024). "These scFv were utilized to coat a PLGA core, resulting in nanoengagers that display anti-CD40 scFv for engaging with macrophages and anti-CLDN18.2 scFv to interact with targeted tumor cells." (PMID 38468289, 2024).
tumor (continued). "Across ILUSTRO and the phase 1 study, the concordance rate (overall percentage agreement) of CLDN18.2 positivity between archival and baseline tumor samples was 61.1% (22/36)." (PMID 38954176, 2024). "This notable benefit in PFS was also observed in patients with moderate to strong CLDN18.2 expression in 70% or more of tumour cells (HR=0.38; 95% CI, 0.23-0.62; p<0.0005)." (PMID 39759684, 2024). "We also focused on intratumoral heterogeneity by comparing the CLDN18 status among different tumor areas (surface vs. center vs. invasive front) and different sample types (biopsy vs. surgical resection)." (PMID 38724721, 2024). "CLDN18.2 positivity was defined as ≥75% of tumor cells showing moderate to strong membranous CLDN18 staining." (PMID 38392051, 2024). "Taken together, these results suggest that GC cells with CLDN18-ARHGAP fusion promotes Treg cell survival and weakens anti-tumor cytotoxicity of NRTs through increased FFA production caused by the PI3K/AKT-mTOR-FAS signaling activation." (PMID 39164472, 2024). "In this study, CLDN18 positivity was defined as ≥75% of tumor cells demonstrating a moderate-to-strong IHC staining, and 4507 patients presented with a valid CLDN18 IHC results, of which 1730 (38.4%) were CLDN18.2-positive tumors." (PMID 38339430, 2024). "The lower degree of cytokine release and robust tumor regression activity indicated that DR30318 was a promising therapeutic agent for CLDN18.2 positive cancers." (PMID 38554200, 2024). "We found that PI3Ki not only repressed tumor growth in GCs with CLDN18-ARHGAP fusion but also restored the TIME with increased CD8+ T-cell infiltration." (PMID 39164472, 2024). "The pivotal phase III SPOTLIGHT and GLOW trials employed the IHC VENTANA CLDN18 (43-14A) assay kit, focusing on patients with moderate-to-strong staining (2+ or 3+) in ≥75% of tumor cells." (PMID 38339430, 2024). "The lower degree of cytokine release and robust tumor regression activity position DR30318 as a promising therapeutic agent for CLDN18.2 positive cancers." (PMID 38554200, 2024). "Nano/CLDN18.2 significantly enhanced the binding affinity of nanoparticles to CLDN18.2-overexpressing tumor cells." (PMID 38468289, 2024). "The analysis categorized studies into two subgroups based on the definition of CLDN18.2 positivity: either staining intensity present in any percentage of tumor cells or staining intensity present in more than 40% of tumor cells." (PMID 38339430, 2024). "The concordance rate of any CLDN18 staining between archival and baseline tumor samples was 88.9% (32/36)." (PMID 38954176, 2024). "Target pairs predicted to independently encode for highly tumor-specific antigens (e.g., MAGEA1, MAGEA4, CLDN18) unsurprisingly resulted in highly tumor-specific antigen pairs as well." (PMID 39515334, 2024). "CLDN18.2 positivity was defined as ≥75% of tumor cells with moderate to strong CLDN18 needed for inclusion." (PMID 38392051, 2024). "Flow cytometry analysis demonstrated that over 80% of CLDN18.2-overexpressing tumor cells were efficiently bound to Nano/CLDN 18.2." (PMID 38468289, 2024). "To visualize the biodistribution of various nanoformulations in nude mice bearing CLDN18.2-overexpressing KPC tumor cells, we loaded the hydrophobic fluorescence dye DiR into the PLGA core of each formulation." (PMID 38468289, 2024). "Similar to the SPOTLIGHT trial, patients with moderate (IHC 2+) or strong (IHC 3+) CLDN18.2 expression in at least 75% of the tumor cells were enrolled." (PMID 38136288, 2023). "In the pancreas, a correlation analysis revealed that lymph node-positive tumours had significantly higher CLDN18.2 expression indicating by the positive cell fractions and membrane staining intensities." (PMID 36969060, 2023). "Immune invasion is a predictor of tumor prognosis, and CLDN18 is correlated with the extent of immune cell infiltration in HCC tumors." (PMID 37438735, 2023).
tumor (continued). "In our patient cohort, positive expression of CLDN18.2 was associated with PD-L1 positivity, and lower CLDN18.2 expression was observed in Borrmann type 3/4 tumours and moderately or highly differentiated tumours." (PMID 37582713, 2023). "Comparative analysis revealed that increased staining intensities consistently corresponded with a greater proportion of tumor cells expressing positive CLDN18." (PMID 37629433, 2023). "Patients with moderate (2+) or strong (3+) CLDN18.2 expression in ≥75% of tumor cells were included." (PMID 38136288, 2023). "In conclusion, CLDN18 was upregulated in the tumor tissues as well as the PBMCs from HCC patients compared to the normal adjacent tissues and the PBMCs from healthy donors respectively." (PMID 37438735, 2023). "Conversely, the cutoff for IHC staining was a strong CLDN18.2 expression (IHC 2+/3+ in ≥75% of tumor cells) in two recent phase III trials (SPOTLIGHT and GLOW)." (PMID 38136288, 2023). "As a single agent in the phase II MONO trial, zolbetuximab ORR was shown to be 9% in CLDN18.2-expressing tumours, and in the subgroup of moderate to strong CLDN18.2 expression (≥70% of tumour cells), the ORR was 14%." (PMID 37370858, 2023). "This significant PFS benefit was maintained even in patients with moderate to strong CLDN18.2 expression in >70% of tumor cells (HR: 0.38, 95% CI: 0.23–0.62)." (PMID 37510761, 2023). "A Japanese retrospective study reported significantly higher CLDN18.2 expression in GCs of the diffuse histological subtype according to the Lauren classification and in high-grade (G3) tumours." (PMID 37582713, 2023). "Regardless of the histological grade, the positive expression of claudin-18.2 in patients with primary PDAC was 94.6%, with 94% of the tumor cells exhibiting high claudin-18.2 expression in IHC staining." (PMID 36959784, 2023). "Claudin proteins are extensively studied, and various claudin proteins, including claudin-1, claudin-4, and claudin-18.2 have high specificity and sensitivity in tumor diagnosis." (PMID 36959784, 2023). "In this model, we used ex vivo cultured Panc02-claudin 18.2 cells after one in vivo tumor passage, which contained approximately 90% CLDN18+ cells with the remaining CLDN18-negative cells, enabling us to explore any endogenous immunity induced by treatment." (PMID 37564658, 2023). "Based on these results, the eligibility criteria in the phase 3 trial (SPOTLIGHT and GLOW trials) were CLDN18.2-positive patients defined as ≥75% of tumor cells with moderate-to-strong CLDN18 staining." (PMID 38136288, 2023). "Positive CLDN18 expression was present in 41/130 (31.5%) surgically resected PDACs and the relative proportion of positive tumor cells and the staining intensity were directly correlated (p < 0.001)." (PMID 37629433, 2023). "In recent years, claudin has been increasingly studied, and many claudin proteins, such as claudin-18.2, claudin-4, and claudin-7 have been demonstrated to be ideal targets for tumor therapy." (PMID 36959784, 2023). "CLDN18.2-specific CAR T cells achieved partial or complete tumor regression in CLDN18.2-positive PDX models." (PMID 37245017, 2023). "Tumors positive for CLDN18 expression were defined as ≥80% of tumor cells with 2+ or 3+ staining intensity in a CLDN18 immunohistochemical assay." (PMID 37629433, 2023). "Patients with moderate (2+) or strong (3+) CLDN18.2 expression in at least 40% of tumor cells were enrolled." (PMID 38136288, 2023). "Conversely, in patients with CLDN18.2 expression in 40–69% of tumor cells, PFS (4.3 vs. 4.1 months, HR 0.71, 95% CI: 0.32–1.57, p = 0.497) and OS (8.3 vs. 7.4 months, HR 0.78, 95% CI: 0.40–1.49, p = 0.401) were not significantly different." (PMID 38136288, 2023). "In terms of tumor stage, CLDN18 expression levels increased with the increase in histological heterogeneity (Spearman: Rho = 0.14, P = 8.94E-03)." (PMID 37438735, 2023).
tumor (continued). "In total, 18 (58.1%) patients with grade 1 tumor differentiation showed positive CLDN18 expression, whereas only 23 (23.2%) patients with grade 2–3 tumor differentiation showed positive CLDN18 expression (p < 0.001)." (PMID 37629433, 2023). "CLDN18 has dichotomous roles in cancers: it can act as a tumour promoter or suppressor depending on the tumour type." (PMID 36969060, 2023). "The CLDN18 staining intensities (0–3+) and relative proportion of positive tumor cells were analyzed by two independent raters." (PMID 37629433, 2023). "Of the patients who achieved clinical benefit, 90% (n = 9/10) had moderate-to-high CLDN18.2 expression in ≥70% of tumor cells." (PMID 38136288, 2023). "On the other hand, there was no statistically significant OS difference (8.3 vs. 7.4 months, HR 0.78, and p = 0.4) in the subgroup of patients with 40–69% of tumour cells positive for CLDN18.2." (PMID 37370858, 2023). "Although many studies have explored the different roles of CLDN18 in tumours, only a few articles have clarified its mechanisms." (PMID 36969060, 2023). "CLDN18 is a promising therapeutic target in gastric and gastroesophageal adenocarcinoma due to its high expression on the surface of tumor cells." (PMID 35861118, 2023). "In a subset of usual‐type ECA cases (13/33, 39.4%), the tumor comprised mucinous epithelium exhibiting an intermediate gastric and usual phenotype and diffuse positive CLDN18 (M) and PAX8 expression." (PMID 35861118, 2023). "DNA CAR copy numbers were examined to represent CAR expression in tumor tissue, which was more significantly elevated in the sequential treatment group than in the CLDN18.2 + CLDN18.2 group (p < 0.05)." (PMID 37046312, 2023). "Patients manifesting with moderate or strong (2+/3+) CLDN18.2 membrane staining intensities in ≥50% of tumor cells were included." (PMID 38136288, 2023). "In another subset of intestinal‐type ECA cases (5/9, 55.6%), the tumor comprised mucinous epithelium exhibiting an intermediate gastric and intestinal phenotype and diffuse positive CLDN18 (M) and CDX2 expression." (PMID 35861118, 2023). "Even areas with different staining intensities and distinct subcellular localization of CLDN18 staining were observed within the same tumor focus." (PMID 35861118, 2023). "In the moderate-to-strong expression group, defined as CLDN18.2 expression in ≥70% of tumour cells, OS increased further to 16.5 vs. 8.9 months with or without zolbetuximab, respectively." (PMID 37370858, 2023). "CLDN18 was significantly upregulated in the PBMCs and tumor tissues of HCC patients, and correlated with the abundance of immune cell infiltration." (PMID 37438735, 2023). "This significant progression free survival benefit was retained in patients with moderate to strong CLDN18.2 expression in > 70% of tumor cells (95% CI 0.23–0.62; HR 0.38)." (PMID 36260159, 2023). "hu7v3-Fc, one of the humanized candidates fused with human IgG1 Fc, showed antibody-dependent cellular cytotoxicity (ADCC) and complement-dependent cytotoxicity (CDC) on CLDN18.2 positive tumor cells in vitro." (PMID 35837391, 2022). "In a subgroup of patients with moderate-to-high CLDN18.2 expression in ≥70% of tumor cells, the overall response rate (ORR) was 14% (n = 4/29)." (PMID 35642043, 2022). "In tumor-adjacent normal tissue, CLDN18.2-postive showed a distinct tumor microenvironment with higher CD4+ FoxP3+ Treg immune cells and CD4+PD-L1+ T cells." (PMID 35811317, 2022). "We considered moderate-to-strong CLDN18.2 expression ≥ 40% of tumor cells as the cut-off for positivity." (PMID 35811317, 2022). "Tumor immune-microenvironmental features and patient survival stratified by CLDN18.2 expression were analyzed using two independent-sample t-tests and log-rank tests, respectively." (PMID 35811317, 2022). "This significant PFS benefit was retained in patients with moderate-to-strong CLDN18.2 expression in ≥70% of tumor cells (HR = 0.38; 95% CI, 0.23–0.62; P < 0.0005)." (PMID 35642043, 2022).
tumor (continued). "In conclusion, CLDN18 is a very good target for determining what is wrong with a tumor and treating it." (PMID 36620607, 2022). "To investigate the features of the tumor immune microenvironment in CLDN18.2-positive GC cancers, we quantified the rate and spatial distribution of immune cells in 80 full-face FFPE samples using m-IHC staining in whole tissue sections." (PMID 35811317, 2022). "The diverse ethnic makeup of the cohort, intra-tumor variation and the limitations of a limited sample size can all be used to explain this variation in CLDN18 expression rate." (PMID 36620607, 2022). "A phase IIa monotherapy study in CLDN18.2-expressing solid tumors, including GC, PC and other tumor types, will begin soon." (PMID 35642043, 2022). "This MB rapidly recognized the RNA of CLDN18.2 and was successfully applied to the circulating tumor cell (CTC) assay." (PMID 35053454, 2022). "ZL-1211 induced tumor cell death more efficiently for all CLDN18.2-high, -medium, and -low clones than benchmark." (PMID 36922936, 2022). "In accordance with the FAST clinical trial (NCT01630083), we defined ≥ 2+ membrane staining intensity in ≥ 40% of tumor cells as CLDN18.2-positive." (PMID 35811317, 2022). "On the other hand, based on the quantitative data from pathomics, we found that the average value of the proportion of CLDN18.2-positive tumor cells in advanced patients was also higher." (PMID 35811317, 2022). "Membranous staining of moderate to strong (2+/3+) intensity was regarded as high expression in tumor cells, and the proportion of CLDN18.2+ cells was calculated." (PMID 35327345, 2022). "When CAR T cells were administered to a xenograft (PDX) model from a CLDN18.2-positive patient with GC, a partial or complete tumor response was observed." (PMID 35053454, 2022). "Any CLDN18 expression (2+ and 3+ intensity in 1–100% tumor cells) was reported in 261/350 (70.6%) patients (234 primary cases, 27 metastases)." (PMID 34834447, 2021). "From the 54 patients enrolled in this trial, 22 were advanced DGC patients with CLDN18.2 expression in ≥ 50% of tumour cells." (PMID 33724653, 2021). "In the FAST study, the addition of zolbetuximab to EOX significantly prolonged median progression-free survival and median overall survival in the overall patient population and the subgroup of patients with tumors expressing CLDN18.2 in ≥ 70% of tumor cells." (PMID 33755863, 2021). "According to our findings, about one third of advanced GCs/GECs exhibit high CLDN18 expression levels (≥2+ in ≥75% of tumor cells) with potential implications for the near clinical practice." (PMID 34834447, 2021). "In the MONO trial moderate or strong (2+/3+) CLDN18 membrane staining intensity in 50% of tumor cells was reported in 54/120 patients (45%) and higher expression levels (2+/3+ in 70% of tumor cells) appeared in 29/120 (24%) of patients." (PMID 34834447, 2021). "In the FAST study CLDN18 expression (≥2+ intensity in ≥40% tumor cells) was found in 334/686 patients (48%) and 249/686 (36.3%) patients had 2+/3+ CLDN18 staining in ≥70% of tumor cells." (PMID 34834447, 2021). "Based on these results, CLDN18-ARHGAP26 fusion is considered as a driver that contributes to aggressive tumor behavior and is a strong candidate for targeted drugs." (PMID 32411236, 2020). "We verified that the alveolar cells expressed relatively high levels of an alveolar marker (CLDN18), whereas both alveolar and tumor epithelial cells expressed relatively high levels of EPCAM, a well-known epithelial marker." (PMID 33083012, 2020). "One hundred eighty of 421 GCs were CLDN18.2-positive; these showed the following distribution of mucin phenotypes: intestinal 29 cases (16.1% of CLDN18.2-positive tumours), gastric 32 cases (17.8%), mixed 78 cases (43.3%), and unclassified 41 cases (22.8%)." (PMID 31332522, 2019).